SERINC1 (serine incorporator 1)
Description:
Enhances the incorporation of serine into phosphatidylserine and sphingolipids.
Synonyms: KIAA1253; TDE1L; TDE2; TMS-2; TMS2
Tractability: Antibody: UniProt predicts a signal peptide or a membrane-spanning region; its Gene Ontology location is reachable by antibodies, with medium confidence. PROTAC: ubiquitination databases record sites on it; its protein half-life has been measured.
Gene: Protein-coding gene on chromosome 6 (122,443,348 to 122,471,854, reverse strand). Ensembl gene ENSG00000111897.
Subcellular location: Endoplasmic reticulum membrane
Subcellular location (Human Protein Atlas): Cytosol
Pathways (Reactome):
Metabolism: Serine metabolism
Gene Ontology:
Molecular function: protein binding; acetyltransferase activator activity; protein-macromolecule adaptor activity
Biological process: membrane biogenesis; phosphatidylserine metabolic process; sphingolipid metabolic process
Cellular component: endoplasmic reticulum membrane; membrane; plasma membrane
Genetic constraint (gnomAD): Loss-of-function variants: 14 observed, 32.39 expected, observed/expected ratio (o/e) 0.43, 90% interval 0.28 to 0.68. The upper end of that interval is the gene's LOEUF score, 0.68, which puts it in group 2 of 6, group 1 being the genes least tolerant of losing a copy. Missense variants: 308 observed, 373.77 expected, observed/expected ratio (o/e) 0.82, 90% interval 0.75 to 0.91. Synonymous variants: 143 observed, 134.42 expected, observed/expected ratio (o/e) 1.06, 90% interval 0.93 to 1.22.
Homologues: Orthologues: chimpanzee SERINC1 (100% identical), macaque SERINC1 (100% identical), dog SERINC1 (98% identical), rabbit SERINC1 (98% identical), guinea pig SERINC1 (96% identical), mouse Serinc1 (96% identical), pig SERINC1 (94% identical), tropical clawed frog serinc1 (83% identical), zebrafish serinc1 (80% identical), Drosophila melanogaster Serinc (41% identical), Caenorhabditis elegans R11H6.2 (41% identical), Caenorhabditis elegans Y57E12AL.1 (40% identical). Paralogues in human: SERINC3 (61% identical), SERINC2 (53% identical), SERINC5 (38% identical), SERINC4 (35% identical).
Diseases named in the same sentence as SERINC1 in open-access papers:
SERINC1 is named in the same sentence as 11 diseases in open-access papers, as found by Europe PMC text mining. Sharing a sentence is not in itself a finding about the gene and the disease. The quoted sentences say what the papers report.
Autoimmunity (1 paper, 2022). The occurrence of an immune reaction against the organism's own cells or tissues. "Serine incorporator 1 (SERINC1) is a presumed carrier protein that promotes the synthesis of serine-derived lipids, which is essential for the function of some immune cells and does not contribute to the connection previously reported between lipid composition and autoimmunity in immune cells." (PMID 35620284, 2022).
diabetes (1 paper, 2015). "Nonetheless, homozygous mutant SB7 mice exhibited a similar diabetes incidence compared to wild-type littermate females, indicating that a minor reduction in Serinc1 expression does not affect T1D pathogenesis." (PMID 26438296, 2015).
ischemic stroke (1 paper, 2022). A stroke disorder caused by obstruction of blood flow to the brain, due to thrombotic (local blood clot formation) or embolic (due to a blood clot or other material traveling from another site) event. "Detailed Profile of the Ischemic Stroke patients with SERINC1 variants." (PMID 35720094, 2022).
liver cancer (1 paper, 2022). An epithelial or non-epithelial malignant neoplasm that arises from the liver. "Of these DEGs, SERINC1 and MYO9B were previously reported as potential driver genes in liver cancer." (PMID 36712866, 2022).
tumor (3 papers, 2016 to 2024). "The tumor volume change rate following SSA treatment was correlated with the expression levels of WWC family member 3 (WWC3) and serine incorporator 1 (SERINC1) and tended to correlate with zinc finger AN1-type containing 3 (ZFAND3) expression." (PMID 36435867, 2022). "ATP2A2 and ARID5B correlated with the GH change rate in the octreotide loading test, and WWC3, SERINC1, and ZFAND3 correlated with the tumor volume change rate after somatostatin analog treatment." (PMID 36435867, 2022). "ATP2A2 and ARID5B were identified as being correlated with the GH change rate in response to octreotide treatment, and WWC3, SERINC1, and ZFAND3 were identified as being correlated with the tumor volume change rate in response to SSA treatment." (PMID 36435867, 2022). "For instance, it has been shown that the expression of the tumor-suppressor gene PTEN can be regulated by its miRNA-mediated competitors VAPA, CNOT6L, SERINC1 or ZNF460." (PMID 26812364, 2016).
infection (1 paper, 2023). The state of being infected such as from the introduction of a foreign agent such as serum, vaccine, antigenic substance or organism. "A reduction in both SERINC1 and SERINC5 was detected 24 h and 48 h post-infection, but this was likely due to the cytopathic effects or the shutoff activity of the virus, since the actin levels were also considerably decreased." (PMID 37766367, 2023).
SERINC1 also shares sentences with these, for which no sentence is quoted: breast carcinoma (1 paper); cancer (1); cardiovascular disease (1); hepatocellular carcinoma (1); SARS-CoV-2 (1).